RNU6-24P (RNA, U6 small nuclear 24, pseudogene)
Synonyms: RNU6-24
Gene: Small nuclear RNA gene on chromosome 17 (76,337,316 to 76,337,422, forward strand). Ensembl gene ENSG00000207169.
Homologues: Orthologues: chimpanzee U6 (100% identical). Paralogues in human: RNU6-1060P (93% identical), RNU6-11P (93% identical), RNU6-12P (93% identical), RNU6-13P (93% identical), RNU6-19P (93% identical), RNU6-32P (93% identical), RNU6-33P (93% identical), RNU6-37P (93% identical), RNU6-43P (93% identical), RNU6-1 (93% identical), RNU6-116P (93% identical), RNU6-17P (93% identical), and 1286 more.